METTL3 (methyltransferase 3, N6-adenosine-methyltransferase complex catalytic subunit)
Diseases named in the same sentence as METTL3 in open-access papers (continued):
Sharing a sentence is not in itself a finding about the gene and the disease.
acute myeloid leukemia (192 papers, 2018 to 2026). Acute myeloid leukemia (AML) is a group of neoplasms arising from precursor cells committed to the myeloid cell-line differentiation. "The E3 ubiquitin ligase RNF113A mediates the ubiquitin/proteasome-dependent degradation of METTL3 through the K48-linked multi-ubiquitin chain, reducing the level of m6A modification to promote the inhibition of acute myeloid leukemia." (PMID 40495163, 2025). "It has been reported that the m6A writer enzyme METTL3 is highly expressed in acute myeloid leukemia (AML) cells, and its loss promotes cell differentiation and decreases cell proliferation in HSPCs." (PMID 37299568, 2023). "Similarly, in METTL3-deficient acute myeloid leukemia cells, c-MYC, Bcl-2, and PTEN protein levels were reduced despite a 2-5 log2-fold increase in mRNA expression." (PMID 38385075, 2024). "In 2017, METTL3, encoding the major m6A methyltransferase, was identified as an essential oncogene in acute myeloid leukemia (AML)." (PMID 36226062, 2022). "In humans, METTL3–METTL14-mediated m6A was found to promote the development of acute myeloid leukemia and maintain leukemia-initiating cells." (PMID 40819104, 2026). "In tumour studies, METTL3 has been found to act as an oncogene in acute myeloid leukaemia but as a tumour suppressor in glioblastoma multiforme." (PMID 40989884, 2025). "An example of a mechanism through which aberrant expression of these proteins promotes oncogenesis is overexpression of METTL3, a methyltransferase or writer, in acute myeloid leukemia (AML)." (PMID 40243425, 2025). "Abnormal overexpression of methyltransferase-like protein 3 (METTL3) plays an important role in the progression of acute myeloid leukemia (AML)." (PMID 40642070, 2025). "STM2457, a potent, selective, and orally active METTL3 catalytic inhibitor, has shown promising anti-tumor effects in various cancers, including acute myeloid leukemia (AML), intrahepatic cholangiocarcinoma (ICC), and neuroblastoma." (PMID 39472692, 2025). "In acute myeloid leukemia, the METTL3 inhibitor STM2457 reduces m6A levels in specific cancer-related genes, enhances their expression, and ultimately extends survival in AML mouse models." (PMID 40002173, 2025). "In acute myeloid leukemia, miR-499a-5p suppresses the progression of the disease by promoting the ubiquitin-proteasomal degradation of METTL3, thereby reducing m6A modification levels." (PMID 40004152, 2025). "Pharmacological inhibition of the m6A methyltransferase (MTase) METTL3, represents a promising strategy for treating acute myeloid leukemia (AML) and likely other cancer types." (PMID 40907939, 2025). "METTL3 inhibitors have demonstrated immunomodulatory and antitumour activities in preclinical cancer models, including glioblastoma and acute myeloid leukemia." (PMID 40793828, 2025). "Consistently, YY1 enhances METTL3 expression as a transcription factor in the human acute myeloid leukemia cell lines Kasumi-1 and THP-1." (PMID 39800682, 2025). "METTL3-mediated m6A deposition is directly involved in the development of acute myeloid leukaemia (AML) by promoting the translation of genes involved in cell growth, differentiation, and apoptosis." (PMID 38470714, 2024). "Treatment of STM2457, an inhibitor targeting the methyltransferase activity of METTL3, results in a specific and significant reduction in stem cell populations within acute myeloid leukemia (AML)." (PMID 39333489, 2024). "Aberrant expression of m6A methyltransferase METTL3 has been reported with oncogenic role in various cancer types, including pancreatic cancer, bladder cancer, liver cancer, and acute myeloid leukemia." (PMID 38233403, 2024). "METTL3 plays a dual role in normal and leukemic myeloid cells by driving the translation of key genes to maintain acute myeloid leukemia (AML) cell proliferation and undifferentiation." (PMID 39295872, 2024).
acute myeloid leukemia (continued). "METTL3 overexpression due to decreased lncRNA MEG3 reduces arabinocytosine (AraC)‐induced apoptosis in acute myeloid leukemia cells." (PMID 39661414, 2024). "STM2457 is a highly potent and selective METTL3 inhibitor discovered recently with therapeutic effect in acute myeloid leukemia." (PMID 38233403, 2024). "Another relevant study revealed that METTL3 regulates the expression of oncogenic MYC in acute myeloid leukaemia through m6A modification." (PMID 39247584, 2024). "STM2457, a novel and selective METTL3 inhibitor, was discovered recently with a therapeutic effect in acute myeloid leukemia." (PMID 38233403, 2024). "In acute myeloid leukemia, the overexpression of METTL3/METTL14 enhances the stability and translation efficiency of c-myc via m6A modifications, thereby accelerating cancer progression." (PMID 38965238, 2024). "METTL3-mediated m6A modification induces the chemo-resistance in acute myeloid leukemia (AML) cells by increasing the stability of integrin subunit alpha 4 (ITGA4) mRNA." (PMID 36835633, 2023). "STM2457 is a highly potent and selective METTL3 inhibitor, which has been tested in acute myeloid leukemia." (PMID 37298373, 2023). "One study revealed that inhibition of METTL3 by the small molecule compound STM2457 is a promising therapeutic strategy for acute myeloid leukemia." (PMID 37537731, 2023). "Studies have shown that the use of STM2457 can lead to reduced METTL3 activity and inhibit the growth of acute myelocytic leukemia." (PMID 37710320, 2023). "For example, METTL3 is abundantly expressed in Acute myelogenous leukemia (AML) and has been identified as a crucial gene for AML cell proliferation by a whole-genome CRISPR dropout screening approach." (PMID 37612540, 2023). "The identified mechanism establishes METTL3 as a pivotal protein for sustaining the leukemic state, emphasizing its therapeutic potential in the context of acute myeloid leukemia." (PMID 38201270, 2023). "METTL3 was highly expressed in acute myeloid leukemia (AML) cells compared to healthy HSPCs or other types of tumor cells." (PMID 36835633, 2023). "METTL3 promotes the growth and tumorigenesis of acute myeloid leukemia cells and inhibits renal cell carcinoma." (PMID 35281840, 2022). "For example, METTL3, the m6A writer, is related to the prognosis and progression of acute myeloid leukaemia (AML), and METTL3 inhibition was reported as a therapeutic strategy for myeloid leukaemia." (PMID 35568866, 2022). "Methyltransferase-like protein 3 (METTL3) plays critical roles in acute myeloid leukemia (AML) progression, however, the mechanism of abnormal overexpression of METTL3 in AML remain elusive." (PMID 36424383, 2022). "STM2457 is a highly potent and selective first-in-class catalytic inhibitor of METTL3, which can reduce acute myeloid leukemia (AML) growth." (PMID 36578520, 2022). "STM2457 and FB23/FB23-2 were small-molecular inhibitors of m6A regulators, preventing the development of human acute myeloid leukemia cells in vitro by specifically suppressing the activities of METTL3 and FTO, respectively, in recent research." (PMID 36120320, 2022). "Recently, attention has been drawn to the METTL3-14 complex regarding its significant roles in the pathogenesis of acute myeloid leukemia (AML), attracting the potential of novel therapeutic targets for the disease." (PMID 35455436, 2022). "METTL3 is shown to be highly explored in advanced acute myeloid leukemia (AML) and has reported roles in lung cancer and HCC." (PMID 36120301, 2022). "In 2017, Professor Tony Kouzaridesd found that overexpression of METTL3 promoted the development of acute myeloid leukemia (AML)." (PMID 35945641, 2022). "For example, the selective primary catalytic inhibitor METTL3 (STM2457) has been reported as a therapeutic strategy for acute myeloid leukemia." (PMID 36114893, 2022).
acute myeloid leukemia (continued). "For example, the depletion of METTL3 in acute myeloid leukemia (AML) cells induced cell differentiation and apoptosis through METTL3-mediated m6A modification on MYC, BCL2 and PTEN mRNA, thus delaying AML progression." (PMID 34996469, 2022). "Recently, a group of researchers reported that METTL3 plays a role in inhibiting adipogenesis of bone marrow mesenchymal stem cells (MSCs) and blocking the chemoresistance of acute myeloid leukemia cells by regulating the PI3K/AKT signaling pathway." (PMID 35574332, 2022). "The mutations of m6A regulatory genes, METTL3, METTL14, YTHDF1, YTHDF2, FTO, and ALKBH5, have been identified in acute lymphoblastic leukemia, multiple myeloma, and acute myeloid leukemia (AML)." (PMID 33898522, 2021). "METTL3 upregulation increases translation of MYC, BCL2 and PTEN mRNAs in acute myeloid leukemia (AML), and METTL3 loss leads to increased levels of phosphorylated AKT, promoting differentiation of hematopoietic stem/progenitor cells (HSPCs)." (PMID 33922187, 2021). "Compared with healthy HSPCs or other types of cancer cells, m6A methyltransferase METTL3 is more abundant in acute myeloid leukemia (AML) cells." (PMID 34745269, 2021). "In adenocarcinoma of the lung, acute myeloid leukemia, and glioma, upregulation of METTL3 and increased m6A levels have been observed." (PMID 35474700, 2021). "METTL3 regulates mRNA expression in this way to facilitate the progression of acute myeloid leukemia." (PMID 34568001, 2021). "It has been extensively reported that c-MYC, a well characterized oncogene involved in the induction of cell proliferation and growth, is targeted by METTL3 in numerous malignancies, including acute myeloid leukemia (AML)." (PMID 34530916, 2021). "CEBPZ has been demonstrated to recruit METTL3 to genes essential for acute myeloid leukaemia such that it can induce m6A modifications that aid their translation." (PMID 33846365, 2021). "Although METTL3 binds to promoters to promote proliferation of tumor cells in acute myeloid leukemia, increased expression often leads to apoptosis of tumor cells in triple‐negative breast cancer." (PMID 34558724, 2021). "Recently, METTL3 small molecule inhibitors have also shown the ability to inhibit the progression of acute myeloid leukaemia (AML) in the body." (PMID 32943100, 2020). "METTL3/14 depletion promotes myeloid differentiation and suppresses the progression of acute myeloid leukemia (AML)." (PMID 32767982, 2020). "METTL3 was up-regulated in acute myeloid leukemia cells, enhanced translation of c-MYC, BCL2, and PTEN mRNAs, blocks cell differentiation and apoptosis, and promotes leukemia progression." (PMID 33363011, 2020). "Recently, a small molecule inhibitor of METTL3 is also shown to curb the development of acute myeloid leukemia (AML) in vivo." (PMID 32244981, 2020). "METTL3 knockdown significantly suppressed cell proliferation, and METTL3 acted as an oncogene in acute myeloid leukemia cells by suppressing Myc expression via a reduction in the m6A level in Myc mRNA." (PMID 31921660, 2019). "In acute myeloid leukemia cells (AMLs), the abundance of METTL3 is elevated compared to that in normal hematopoietic stem/progenitor cells (HSPCs)." (PMID 31921664, 2019). "METTL3 has been shown to have a tumor-promoting role in many cancers and its inhibition through small molecules has recently been proposed as a therapeutic strategy for acute myeloid leukemia (AML)." (PMID 39528654, 2024). "For example, STM2457, a small molecule inhibitor of METTL3 with in vivo activity, was shown to effectively disrupt the proliferation and expansion of leukemia cells, thereby inhibiting cancer progression in various mouse models of acute myeloid leukemia." (PMID 38267663, 2024). "This is, for instance, the case for METTL3 inhibitors in acute myeloid leukemia." (PMID 38675956, 2024).
acute myeloid leukemia (continued). "Further, we show that a METTL3 inhibitor, which has been shown to be effective against acute myeloid leukaemia and in an improved version is currently undergoing clinical trials for solid tumours (identifier NCT05584111), leads to inhibition of all three viruses." (PMID 37306620, 2023). "miCLIP analysis showed that METTL3 enhanced the m6A methylation of target genes such as Bcl2, Myc and Pten in the human acute myeloid leukaemia (AML) MOLM-13 cell line, which promoted the mRNA translation of these genes, thereby retaining pluripotency properties and inhibiting cell differentiation." (PMID 36407103, 2022). "A previous study showed that METTL3 was overexpressed in acute myeloid leukemia, in which it methylated BCL2, PTEN, and c-Myc mRNAs, leading to boosted translation and the inhibition of cell apoptosis and differentiation, thereby promoting leukemia progression." (PMID 36360287, 2022). "Considering that m6A modifications are relevant to cancer development and catalyzed predominately by the METTL3-METTL14 methyltransferase complex, a selective METTL3 inhibitor has recently been developed and exhibits a significant therapeutic effect in acute myeloid leukemia." (PMID 35279145, 2022). "The writer METTL3 was early noticed because of its overexpression in acute myeloid leukemia (AML)." (PMID 33732286, 2021). "As an oncogene, METTL3 depletion could result in cell cycle arrest in acute myeloid leukemia and bladder cancer in a m6A-dependent manner." (PMID 33648590, 2021). "For example, METTL3 is overexpressed in acute myeloid leukaemia (AML)." (PMID 33461542, 2021). "For example, METTL3 is highly expressed in acute myeloid leukemia (AML) cells." (PMID 33816306, 2021). "In addition, in acute myeloid leukaemia (AML), METTL3 depletion caused a favourable outcome by delaying the occurrence of disease through the promotion of the terminal myeloid differentiation of HSPCs and impairment of AML cell survival." (PMID 33431045, 2021). "The gene regulated by METTL3 in this way is necessary for acute myeloid leukemia, suggesting that METTL3 may be a therapeutic target for acute myeloid leukemia." (PMID 32754191, 2020). "Given recent data arguing that the METTL3-mediated addition of m6A residues to mRNAs also promotes the uncontrolled growth of acute myeloid leukemia cells, such a compound might also prove useful in the treatment of certain types of cancer." (PMID 29447282, 2018). "Core components of the m6A machinery, including METTL3, METTL14, FTO, and ALKBH5, have been implicated in acute myeloid leukemia (AML) pathogenesis." (PMID 40973767, 2025). "METTL3 on the other hand is a critical player acute myeloid leukemia (AML), which has led to the development of METTL3 inhibitors, some of which are undergoing Phase 1 clinical trials (Identifier: NCT05584111)." (PMID 40219966, 2025). "For instance, inhibition of the methyltransferase METTL3 has been shown to significantly suppress the progression of acute myeloid leukemia (AML)." (PMID 40698864, 2025). "METTL3 and METTL14, key components of the m6A writer complex, are frequently overexpressed in various malignancies, including acute myeloid leukemia (AML), where aberrant methylation has been linked to the upregulation of oncogenic transcription." (PMID 41245600, 2025). "An METTL3 inhibitor, UZH1a, was identified by the Caflisch group and has shown high nanomolar potency and good selectivity and cellular activity where in vitro demonstrated a reduction exclusively in the m6A/A ratio within acute myeloid leukemia, osteosarcoma, and kidney cancer cells." (PMID 39459530, 2024). "On mRNA, it is catalyzed by the METTL3–14heterodimer complex, which plays a key role in acute myeloid leukemia(AML) and other types of blood cancers and solid tumors." (PMID 38425900, 2024).
acute myeloid leukemia (continued). "The expression of METTL3 has been shown to be increased in acute myeloid leukemia (AML) patients, suppressing cell differentiation and apoptosis, and promoting cell proliferation through increased translation of c-MYC, BCL2, and PTEN." (PMID 39457524, 2024). "Previous studies reported that METTL3 plays an oncogenic role in acute myeloid leukaemia through diverse downstream targets, whereas other studies suggested that either increased or decreased METTL3 expression could promote the self-renewal and tumorigenicity of glioma stem-like cells, respectively." (PMID 36765397, 2023). "In acute myeloid leukemia (AML), METTL3 promotes leukemogenesis and inhibits myeloid differentiation, potentially through the targeting of oncogenic genes such as MYC and CEBPA." (PMID 38012755, 2023). "The first evidence of specificity comes from a study on the role of METTL3 in acute myeloid leukemia (AML)." (PMID 38201270, 2023). "METTL3 is associated with the occurrence and maintenance of acute myeloid leukemia (AML), so one study has explored whether STM2457, as a small molecule specific inhibitor of METTL3 enzyme, targeting METTL3 enzyme activity has anti-leukemia therapeutic potential." (PMID 37020540, 2023). "In malignant hematological diseases, such as acute myeloid leukemia (AML), the quantity of the mRNA modified by METTL3 in blood cells is significantly increased." (PMID 36896007, 2023). "In addition, previous research revealed that the METTL3-induced m6A modification in the coding sequence may alleviate ribosome stalling and thus improve mRNA translation in acute myeloid leukemia." (PMID 37550765, 2023). "For example, promoter-bound m6A methylase METTL3 maintains acute myeloid leukemia (AML) through m6A-dependent translation control." (PMID 38933901, 2022). "For example, in acute myeloid leukemia (AML), overexpressed METTL3 promotes cell proliferation and inhibits cell differentiation by modifying c-MYC, BCL-2, and PTEN with m6A." (PMID 36293529, 2022). "For instance, METTL3 is upregulated in acute myeloid leukemia (AML) and is a necessary gene to preserve the undifferentiated phenotype in AML." (PMID 35886072, 2022). "STM2457, the selective catalytic inhibitor of METTL3, has been found to reduce the growth of acute myeloid leukemia (AML) and promote differentiation and apoptosis, thus preventing and slowing AML progression in mouse models." (PMID 36457997, 2022). "In addition, another study confirmed that METTL3 could maintain acute myeloid leukemia cells in an undifferentiated state in vivo, thereby preventing the occurrence and development of myeloid leukemia." (PMID 36360287, 2022). "In acute myeloid leukemia (AML), METTL3 promotes oncogenes SP1 translation by decreasing ribosome stalling." (PMID 34150845, 2021). "A mechanistic study in acute myeloid leukemia (AML) found that METTL3 is recruited by the transcription factor CHOP (CEBPζ) and methylates CHOP-regulated transcripts." (PMID 34093133, 2021). "Recent studies demonstrated that loss of METTL3, METTL14, or FTO weakens acute myeloid leukemia (AML) propagation, whereas inactivation of METTL3 and METTL14 has deleterious consequences for normal HSC maintenance." (PMID 33156926, 2021). "In acute myeloid leukemia (AML), both METTL3 and METTL14 can directly target MYC to enhance its translation efficacy and inhibit differentiation and increase proliferation." (PMID 34315512, 2021). "In acute myeloid leukemia (AML), METTL3 and METTL14 have been already described as regulators of mRNA translation." (PMID 34561421, 2021). "Comparing with healthy HSPCs or other types of tumor cells, the expression of METTL3 at both transcriptional and translational levels was dramatically enhanced in acute myeloid leukemia (AML) cells." (PMID 30405719, 2018).